PCAT5 (prostate cancer associated transcript 5)
Synonyms: TPCAT-10-36067; LINC01452
Gene: Long non-coding RNA gene on chromosome 10 (35,778,302 to 35,800,920, forward strand). Ensembl gene ENSG00000280719.
Diseases named in the same sentence as PCAT5 in open-access papers:
PCAT5 is named in the same sentence as 4 diseases in open-access papers, as found by Europe PMC text mining. Sharing a sentence is not in itself a finding about the gene and the disease. The quoted sentences say what the papers report.
prostate carcinoma (3 papers, 2017 to 2024). A carcinoma that arises from epithelial cells of the prostate gland. "For instance, PCAT5 is a long noncoding RNA regulated by the ERG, an active transcription factor common in human prostate cancer." (PMID 33033484, 2020).
cancer (1 paper, 2020). A tumor composed of atypical neoplastic, often pleomorphic cells that invade other tissues. "When treating males separately, associations between smoking initiation and PCAT5/ANKRD30A, two genes involved in cancer development, were identified and replicated." (PMID 33033484, 2020). "Regarding PCAT5 and ANKRD30A, it is reported that both of them are related to cancer progression." (PMID 33033484, 2020).
tumor (1 paper, 2024). "Compared with the control group, Lin28B knockdown reduce the average volume of xenografts in nude mice, while overexpression of PCAT5 can save the tumor growth inhibition of Lin28B knockdown." (PMID 38565547, 2024). "In order to confirm the role of LIN28B, PCAT5, and IGF2BP3 in tumor growth in vivo, we subcutaneously injected Ishikawa or HEC-1A cells with knockdown of LIN28B, PCAT5 and IGF2BP3 respectively, or a combined knockdown of LIN28B + PCAT5 + IGF2BP3 to construct a xenograft tumor model in nude mice." (PMID 38565547, 2024). "moreover, compared with the control group, PCAT5 knockdown significantly reduce the average volume of xenografts in nude mice, and overexpression of IGF2BP3 could save tumor growth inhibition of PCAT5 knockdown." (PMID 38565547, 2024). "Finally, our in vivo study showed that knockdown of LIN28B, PCAT5, and IGF2BP3 could inhibit tumor growth in xenografted tumors, and mice injected with the combination of these three agents showed minimal xenografted tumor volume and weight." (PMID 38565547, 2024).
PCAT5 also shares sentences with these, for which no sentence is quoted: endometrial cancer (1 paper).